CD27 (CD27 molecule)
Diseases named in the same sentence as CD27 in open-access papers (continued):
Sharing a sentence is not in itself a finding about the gene and the disease.
Stroke (9 papers, 2020 to 2025). Sudden impairment of blood flow to a part of the brain due to occlusion or rupture of an artery to the brain. "We identified a previously unrecognized GZMK+CD8+CD27+CCR7+ T-cell subset in AIS patients, named stroke-associated T (Tsa) cells, which was significantly positively correlated with the severity of clinical symptoms." (PMID 40659887, 2025). "Through single-cell RNA sequencing, we identified a novel GZMK+CD8+CD27+CCR7+ T-cell subset in patients with acute ischemic stroke (AIS), which we designated stroke-associated T (Tsa) cells." (PMID 40659887, 2025). "Additionally, an elevated susceptibility to stroke was linked to an increase in the percentage of CD39+ resting Tregs and heightened CD27 expression on IgD- CD38+ cells." (PMID 38887301, 2024). "Although CD27+ T cells have proven to be involved in the pathogenesis of meningitis, there is still a lack of direct evidence that the soluble CD27 protein is associated with PNBM or stroke." (PMID 37409018, 2023). "However, our findings align with this complexity, demonstrating that certain phenotypes associated with B cell activity, such as CD19 on CD24+ CD27+, CD20 on IgD- CD27-, CD25 on naive-mature B cell, CD27 on IgD- CD38br, IgD+CD38dim %B cell are linked to an increased risk of stroke." (PMID 38894965, 2024). "Key B cell subtypes relevant to stroke can be classified as follows: plasmablasts (CD27+CD38+), unswitched memory B cells (CD27+IgD+), switched memory B cells (CD27+IgD−), naïve B cells (CD27−IgD+), and double-negative B cells (CD27−IgD−)." (PMID 39633897, 2024). "We next identified memory B cell subsets based on their expression of IgD and CD27, which revealed a decrease in the frequency of unswitched memory B cells, but this did not correlate with the stroke severity." (PMID 33205448, 2021).
atherosclerosis (8 papers, 2011 to 2025). A disease characterized by the build-up of fatty material and calcium deposition in the arterial wall resulting in partial or complete occlusion of the arterial lumen. "ApoE−/− mice reconstituted with CD27-deficient bone marrow show significantly larger plaque sizes and a decreased abundance of Tregs compared to mice receiving CD27+/+ApoE−/− bone marrow, particularly in the early stages of atherosclerosis." (PMID 39926714, 2024). "Notably, adoptive transfer of wild-type Tregs into CD27-deficient mice reversed this phenotype, resulting in even smaller lesions than those in control mice, suggesting that CD27+ Tregs play a protective role against atherosclerosis." (PMID 39926714, 2024). "Loss of Cd47 led to an enrichment of CD90+CD27+ IFN-γ producing NK cells and depletion of NK cells blocked the increased atherosclerosis observed in Cd47−/− mice." (PMID 31337788, 2019). "Evidence for the role of CD27:CD70 in atherosclerosis is conflicting as ruptured atherosclerotic plaques expressed higher CD70 than those in stable lesions, and CD70 transgenic mice attenuated atherosclerotic development." (PMID 28738836, 2017). "Given the age-related decline in circulating CD20+CD27+CD43+ cells and the multiple covariates linked to atherosclerosis that exist in a human population, this study will need a large number of subjects and a large amount of investigator perseverance." (PMID 23248624, 2012). "CD70 deficiency reduced spleen Treg in ApoE−/− mice and CD27 deficiency reduced Treg in solid tumor in mice, suggesting that CD27:CD70 may have an immunosuppressive role in atherosclerosis and tumor growth." (PMID 28738836, 2017). "The CD27:CD70 reverse stimulatory immune checkpoint towards APC may be protective for atherosclerosis." (PMID 28738836, 2017). "Notably, the percentage of circulating human CD27+ B cells belonging to the B-1 subset declines with age in a pattern strikingly similar to the inverse of the age-related increase in atherosclerosis prevalence." (PMID 23248624, 2012). "However, thymic CD27−/− Tregs exhibit increased apoptosis and express fewer proliferation markers in vivo, indicating that CD27 deficiency impairs thymic output of Tregs, contributing to the exacerbation of atherosclerosis, particularly in the initial stages." (PMID 39926714, 2024). "In contrast, the individuals with atherosclerosis in our study demonstrated a reduction in the expression of genes which contribute to T cell activation and maturation (CD3, CD3E, CD6, CD27)." (PMID 21698167, 2011). "Unlike conventional costimulatory molecules, CD27/CD70 activates T cells while providing significant protection against atherosclerosis." (PMID 41268556, 2025).
common variable immunodeficiency (8 papers, 2005 to 2023). "The six-years-old index patient K1-III.3 was diagnosed with common variable immunodeficiency (CVID) and displayed loss of IgD expression in almost half of her IgM+CD27- naïve B cells." (PMID 36776874, 2023). "In the work reported herein, we analyzed the frequency of peripheral blood plasmacytoid DCs (pDCs) and myeloid DCs (mDCs) in a cohort of 44 adults with common variable immunodeficiency (CVID) classified according to their CD27 membrane expression status on B cells." (PMID 16207321, 2005).
acute myeloid leukemia (7 papers, 2018 to 2025). Acute myeloid leukemia (AML) is a group of neoplasms arising from precursor cells committed to the myeloid cell-line differentiation. "Moreover, blockade of the CD70/CD27 interaction has been associated with the downregulation of stemness-associated genes in acute myeloid leukemia blasts, suggesting that CD70/CD27 signaling contributes to a more undifferentiated and malignant state." (PMID 40876452, 2025). "In acute myeloid leukemia (AML), blocking the interaction between CD70/CD27 may promote the asymmetric differentiation and division of AML cells, further inhibiting tumor proliferation." (PMID 36358792, 2022). "Although absent from normal HSCs, constitutive expression of CD27 is detected on LSCs of acute myeloid leukemia (AML) and chronic myeloid leukemia (CML) patients." (PMID 34991665, 2022).
AIDS (7 papers, 2012 to 2024). A syndrome resulting from the acquired deficiency of cellular immunity caused by the human immunodeficiency virus (HIV). "sIL-2Rα, sIL-6R, IL-10, IP-10, MCP-1, TNF-α, eotaxin, BLC-BCA1, CD27 and sTNFR-2 were all statistically significantly higher in AIDS-KS than controls." (PMID 33521162, 2018). "Only two SIBC lines (AIDS‐NHL‐SIBC309 and HIV‐SIBC450) have a lower proportion of CD19+/CD20+CD27+ memory B cells, accounting for ~48% in SIBC309 and ~77% in SIBC450." (PMID 31538749, 2019). "Those with statistically significantly higher values in the AIDS-KS cases were IFN-γ, MCP-1, IFN-γ, sIL-6R, sIL-2Rα, IL-10, BLC-BCA1, CD27, sTNFR-2, sCD14, TNF-α, and IP-10." (PMID 33521162, 2018). "The SIBC lines of this study presented CD19+/CD20+CD27+ memory B cells as a main population, while two AIDS‐NHL‐SIBC309 and HIV‐SIBC450 harbored a subpopulation of CD19+/CD20+CD27− naïve B cells, suggesting that SIBCs were derived from either a CD27‐ germinal center (GC) or CD27+ post‐GC B cell." (PMID 31538749, 2019). "Moreover, serum levels of the soluble forms of CD23 and CD27 were increased in AIDS patients who went on to develop lymphomas, including DLBCL, when compared to HIV+ or even to AIDS subjects who did not progress to cancer." (PMID 33996608, 2021). "If integration into CD27 affects the differentiation or activation of host CD4+ T cells, such arrest may contribute to the observed lack of help by CD4+ T cells and the development of AIDS." (PMID 23209625, 2012).
asthma (7 papers, 2018 to 2024). "However, it has been reported that people with asthma have decreased percentages of CD24+CD27+ B cells, which are required for the induction of IL10+ T cells." (PMID 29881878, 2018). "Furthermore, this study showed that an increase in the frequency of ILC3s and a decrease in γδ T cells and CD27-negative CD4+T cells during the off-season were associated with an improvement in asthma symptoms in patients with SAR-JCP during the in-season." (PMID 35454107, 2022). "γδ T cells are also involved in asthma pathogenesis and Th2 inflammation through IL-17 production, and this trend is considered to be similar to that of CD27-negative CD4+ T cells." (PMID 35454107, 2022). "In addition to the increase in ILC3s after SLIT, these findings suggest that the improvement of asthma symptoms during the JCP dispersal season after SLIT was associated with an increase in peripheral blood ILC3s and decrease in CD27-negative CD4+ and γδ T cells during the off-season." (PMID 35454107, 2022). "The findings suggest that SLIT for asthma patients with SAR-JCP contributed to the further stabilization of asthma symptoms, and changes in peripheral blood CD27-negative CD4+ T cells, γδ T cells, ILC1s, and ILC3s during the off-season were associated with improved asthma symptoms after SLIT." (PMID 35454107, 2022).
Cirrhosis (7 papers, 2016 to 2025). A chronic disorder of the liver in which liver tissue becomes scarred and is partially replaced by regenerative nodules and fibrotic tissue resulting in loss of liver function. "Dysfunctional B-cell activation in cirrhosis resulting from hepatitis C infection associated with the disappearance of CD27-positive B-cell population." (PMID 39273468, 2024). "This study has shown that cirrhosis is associated with profound reductions of CD27+IgM+ B-cells, a subset of memory B-cells thought to be generated in response to T-independent antigens." (PMID 39273468, 2024). "More specifically, cirrhosis is characterized by decreased numbers of T helper and cytotoxic T cells, as well as loss of CD27+ memory B cells." (PMID 35215801, 2022). "In our previous work, reduction of CD27+ B-cell frequency in cirrhosis was strongly associated with reduced B-cell cytokine production as well as impaired allostimulation-induced CD4+ T-cell proliferation." (PMID 27857173, 2016). "In contrast, CD27 knockout significantly impaired T cell differentiation, and regulation of cell-cell adhesion mediated by integrin, revealing that adaptive immune hyperactivation is mechanistically linked to cirrhosis progression through this hub gene." (PMID 41202080, 2025). "We suspect that cirrhosis-related CD27+ memory B-cell loss could therefore be a critical contributor to the functional immunodeficiency present in patients with cirrhosis." (PMID 27857173, 2016). "This study is the first to reveal a causal relationship between hypothyroidism and cirrhosis, potentially driven by immune dysregulation mediated by HLA-DQA1 and CD27." (PMID 41202080, 2025). "Our scRNA data further confirmed this finding: as cirrhosis progresses, CD27 expression levels in CD8+ T cells increase, closely correlating with enhanced interactions between CD8+ T cells and macrophages." (PMID 41202080, 2025). "Increased CXCL-10 levels promote NK cell apoptosis, which contributes to systemic immunosuppression, and the IgG production and costimulatory functions of CD27 memory B cells are impaired in cirrhosis." (PMID 39273468, 2024). "We also noticed a marked elevation of CD27+CD38++ plasma cells in patients with ACLF (p < 0.05 for ACLF vs. cirrhosis and for ACLF vs. HC)." (PMID 36505417, 2022). "The reduction of circulating peripheral CD27+ memory B-cell in cirrhosis most likely results from enhanced Fas-mediated apoptosis in vivo mediated by increased exposure to cell-bound and surface FasL, and modulated by LPS." (PMID 27857173, 2016). "Peripheral CD27+ memory B-cells become quantitatively reduced and dysfunctional in patients with cirrhosis through poorly characterized mechanisms." (PMID 27857173, 2016). "We conclude that peripheral CD27+ memory B-cells in cirrhosis exhibit increased sensitivity to Fas-induced apoptosis in an activation-dependent manner to which endotoxin contributes, associated with reduced frequency of circulating memory B-cells." (PMID 27857173, 2016). "Consistent with our prior observation, the frequency of CD27+ memory B-cells was reduced in patients with cirrhosis (CIR) relative to healthy donors (HD) (28.3 ± 3.4 in HD versus 19.5 ± 2.4 in CIR, p = 0.029)." (PMID 27857173, 2016). "Further correlation analysis between HLA-DQA1 and the gene sets linked to the top 10 key biological pathways revealed that CD27 stood out as the only gene showing both a strong correlation with HLA-DQA1 and consistent expression patterns across hypothyroidism and cirrhosis." (PMID 41202080, 2025). "In addition to HLA-DQA1, our study identified CD27 as another key molecule linking hypothyroidism and cirrhosis." (PMID 41202080, 2025). "We found that the ACLF liver harbored reduced fraction of naïve B cells and elevated percentage of CD27+CD21− activated memory B cells (AM), CD27−CD21− atypical memory B cells (atMBC), CD27+IgD−IgM+(IgM+ memory B cells), and CD27+CD38++ plasma cells than cirrhosis and healthy controls." (PMID 36505417, 2022).
Cirrhosis (continued). "To examine B cell phenotypes in D-LC caused by HBV, we performed flow cytometry using a panel of 11 markers (CD19, CD10, CD38, IgD, CD21, CD27, CCR7, CXCR3, CXCR4, CXCR5, and IL-21R) and demonstrated the changes of B cell subsets for the first time in HBV-associated advanced cirrhosis." (PMID 34248941, 2021). "Specifically, in cirrhosis, HLA-DQA1 exhibited an outstanding area under the curve (AUC) of 0.973, while CD27 also showed robust performance with an AUC of 0.846." (PMID 41202080, 2025). "As a member of the tumor necrosis factor receptor superfamily, CD27 plays crucial roles in the pathogenesis of both autoimmune thyroid disease (AITD) and cirrhosis." (PMID 41202080, 2025). "Our group identified a small increase in CD27−CD21− hypoproliferative tissue-like memory B-cells in patients with viral hepatitis-related cirrhosis that could not numerically account for the disappearance of CD27+ B-cells nor account for the similar reduction observed in non-viral-related cirrhosis." (PMID 27857173, 2016).
colorectal cancer (7 papers, 2014 to 2026). A primary or metastatic malignant neoplasm that affects the colon or rectum. "A significantly greater frequency of CD27+IgD- MBCs was found in the peripheral blood of patients with colorectal cancer." (PMID 39611128, 2024). "Also, in the same study CD27+IgD− memory B cells were elevated in colorectal cancer tumor compared to peripheral blood of healthy controls (p < 0.005) and IgD+/CD27−/CD38− B cells are decreased in tumor samples of colorectal cancer patients." (PMID 41008839, 2025). "To investigate this, we combined anti-mouse CD27 (mCD27) with anti-mCTLA-433,34 in the CT26 colorectal cancer model." (PMID 35288635, 2022).
latent infection (7 papers, 2009 to 2025). "CD27 and CD26 were among the markers which best discriminated fast and slow responders, consistently with prior studies associating CD27 and CCR4 expression in Mtb-specific CD4+ T-cells with active TB compared to latent infection." (PMID 35392094, 2022). "EBV reactivation may drive the expansion of CD27+ B lymphoblasts with latent infection in peripheral blood." (PMID 40746349, 2025). "The finding that the CMV-specific CD8 T cell phenotype in elderly individuals is similar to the predominant phenotype of CD8 T cells as a whole, suggest that latent infection with CMV can be considered as a major force contributing to the differentiation of CD8 T cells into CD27- CD28- cells." (PMID 19715573, 2009). "The results of our conventional analyses show the performance of CD27, CD38, HLA-DR and Ki-67 to discriminate active disease from latent infection." (PMID 35935194, 2022). "CD27 is a member of Tumor necrosis factor receptor (TNFR) family members that play key roles in control of both acute and persistent or latent infections." (PMID 26322025, 2015). "In this paper, we aim to study the expression of the CD27, CD38, HLA-DR and Ki-67 markers in Mtb-specific CD4+ T-cells by performing a side by side comparison of their performance on characterizing active disease and latent infection." (PMID 35935194, 2022). "Thus, neither the expression of CD27 on bulk CD4 T lymphocytes, nor the frequency of Mtb-specific IFN-γ producing CD4 T cells, discriminated active TB from latent infection." (PMID 22937086, 2012).
non-small cell lung carcinoma (7 papers, 2015 to 2025). A group of at least three distinct histological types of lung cancer, including non-small cell squamous cell carcinoma, adenocarcinoma, and large cell carcinoma. "We have assessed the co-expression of CD70 and CD27 in non-small cell lung cancer (NSCLC) by immunohistochemistry to explore a correlation between expression of the protein and tumor histologic subtype, genetic aberrations and prognosis." (PMID 25951351, 2015). "A similar pattern has been reported in non-small cell lung cancer (NSCLC) CD8+ tumor infiltrating lymphocytes (TILS), where PD-1-high cells are earlier stage CD27+ T cells, while KLRG1+ cells are later-stage CD27– T cells that are not PD-1-high." (PMID 39832302, 2025). "Costimulatory molecules expressed by most CD8+ TRM cell subsets are CD27 and CD28, and in non-small cell carcinoma, the CD69+CD8+ TILs express CD27 and CD28." (PMID 33467606, 2021).
Obesity (7 papers, 2015 to 2023). Accumulation of substantial excess body fat. "In the hip joint, IPA analysis of the obesity‐associated DEGs revealed significant canonical pathways involved in immune signalling pathways ‘CD27 and CD40 signaling’ as well as ‘osteoarthritis’ and ‘senescence’ pathways." (PMID 37006170, 2023). "We found a significant expansion of IgD+CD27- naïve B cells in individuals with obesity compared to lean controls, which was normalised to control levels following surgery." (PMID 37463992, 2023). "One of our most prominent observations was that the disrupted naïve and memory cell balance – with expansion of IgD+CD27- naïve B cells and reduction in CD24hiCD38lo memory B cells – in obesity was normalised following bariatric surgery." (PMID 37463992, 2023). "Furthermore, this implies that maternal obesity drives dNK cell differentiation toward relatively mature CD11b+CD27+ subset but prevents its further maturation from CD11b+CD27+ to CD11b+CD27− subset at the maternal–fetal interface in spontaneous abortion mice." (PMID 34177956, 2021). "To further interrogate how functional differentiation pathways are affected by obesity and bariatric surgery, we next assessed CXCR5+CD11c-IgD-CD27- DN1 and CD11c+CXCR5-IgD-CD27- DN2 B cell subset as well as CD27+CD38++ plasmablast frequencies." (PMID 37463992, 2023). "We have previously shown that obesity also increases blood frequencies of the subset of double negative (DN) B cells (CD19+CD27-IgD-) which represents the most inflammatory B cell subset." (PMID 33760825, 2021). "Additionally, diet-induced obesity does not appear to affect the maintenance of pre-existing long-term memory CD8 + CD27 + T cells, as well as their cytokine production and functions." (PMID 35069589, 2021). "To determine whether obesity impacts γδ T cell maturation we compared CD27 and CD45RA expression on Vγ9Vδ2 T cells in obese and nonobese donors." (PMID 25785862, 2015). "Furthermore, the NK cell maturation state was also changed between AP and NP mice, with obesity combined with AP driving the dNK cell differentiation from immature CD11b−CD27− or CD11b−CD27+ to relatively mature CD11b+CD27+ phenotypes and prevented further maturation into the CD11b+CD27− subset." (PMID 34177956, 2021).